CCL5 (C-C motif chemokine ligand 5)
Diseases named in the same sentence as CCL5 in open-access papers (continued):
Sharing a sentence is not in itself a finding about the gene and the disease.
Allergy (20 papers, 2009 to 2025). An allergy is an immune response or reaction to substances that are usually not harmful. "Chemokine receptors (CXCR1 and CXCR2) of activated mast cells receive cytokine (CCL5) signals, and stimulated mast cells migrate into the tissue to release histamine, lipid mediators, and other inflammatory cytokines and chemokines to cause serious allergy and inflammation." (PMID 25861366, 2015). "Eotaxins (ccl11 and ccl24) and regulated on activation normal T cell expressed and secreted (RANTES or ccl5) are potent chemoattractants that mediate eosinophil chemotaxis and allergy signaling." (PMID 30252910, 2018). "CCL5 is an eosinophil chemoattactrant that is thought to play a role in the accumulation of eosinophils often observed in middle ear effusions of OM with allergy." (PMID 19728873, 2009). "It was shown that TLR4 or TLR9 stimulation combined with FcεRI activation by anti-IgE resulted in a synergistic increase of IL-4, CXCL8, IL-13 and RANTES/CCL5, all of which are thought to enhance IgE-mediated responses, such as allergy or parasitic infection." (PMID 26870962, 2016).
myocardial infarction (20 papers, 2011 to 2024). Gross necrosis of the myocardium, as a result of interruption of the blood supply to the area, as in coronary thrombosis. "This case-control study aimed at exploring the association between coronary atherosclerosis manifested by myocardial infarction and two functional polymorphisms in the RANTES (CCL5) gene, the product of which is involved in atherosclerotic inflammation." (PMID 21547257, 2011). "Similarly, TNFα, MCP-1, and CCL-5 mediate pro-inflammatory effects via mechanisms associated with increased vascular injury leading to AD and myocardial infarction." (PMID 33626069, 2021). "Possibly the heteromer formation of CCL5•CXCL4 also plays a role because inhibition of CCL5•CXCL4 preserves heart function after myocardial infarction by attenuating leukocyte recruitment and NETosis." (PMID 37954596, 2023). "Whereas the functions and the antagonism of CCL5 in myocardial infarction have been extensively studied, less is known about the role of CXCL4." (PMID 30006564, 2018). "For instance, higher CCL3 (and CCL5) concentrations were identified in patients with acute myocardial infarction as compared with controls." (PMID 27573044, 2016). "The finding of up-regulated CCL5/RANTES in human atherosclerotic plaques corroborates with the association demonstrated between CCL5/RANTES and unstable angina pectoris and myocardial infarction." (PMID 22011432, 2011). "Furthermore, treatment with anti-CCL5 after myocardial infarction results in reduced neutrophil and macrophage infiltration and smaller infarction size." (PMID 30308065, 2018). "CCL5/RANTES signaling recruits leukocytes to the site and generally act pro-inflammatory, however, there has been some contradicting data, whether higher concentrations of CCL5/RANTES show a positive or negative effect after acute myocardial infarction." (PMID 33123511, 2020).
Parkinson disease (20 papers, 2014 to 2024). A progressive degenerative disorder of the central nervous system characterized by loss of dopamine producing neurons in the substantia nigra and the presence of Lewy bodies in the substantia nigra and locus coeruleus. "CCL5 is implicated in other age-related neurodegenerative diseases, such as Parkinson disease." (PMID 32324857, 2020). "Of note, GIRK channels play a direct role in Parkinson’s pathophysiology, and upregulation of serum CCL5 is correlated with disease severity." (PMID 34490352, 2021). "We observed significant elevation of the chemokine CCL5, previously illustrated to be elevated in Alzheimer’s and Parkinson’s, with a linear correlation to clinical severity in the latter disease." (PMID 33707598, 2021). "Furthermore, elevated levels of CCL5 have been reported in patients with GA AMD compared to controls and also in Parkinson's disease." (PMID 34869411, 2021).
type 2 diabetes (20 papers, 2008 to 2025). "In a small network, known causal components ADA and CD26 (DPP4) form a cascade with the predicted causal component CD44 (green node) connected by RANTES (CCL5) (blue node), which harbors promoter polymorphisms associated with type 2 diabetes." (PMID 20815942, 2010). "A meta-analysis concluded that the concentration of CCL2 and CCL5 were significantly higher in type 2 diabetic patients when compared to controls." (PMID 39518420, 2024). "Despite limitations, this study demonstrates a distinctive inflammatory tear cytokine profile (elevated IL-6, CXCL8, IL-15, CCL5, VEGF) in type 2 diabetes patients, contrasting with decreased systemic inflammation." (PMID 41030257, 2025). "Correlating these data, we can assume that CCL2, CCL5, IL-6, IL-1β, and leptin can play a significant role in MDSC recruitment in the adipose tissue of patients with type 2 diabetes." (PMID 39518420, 2024). "Under the metabolic environment of type 2 diabetes mellitus (T2DM), activated platelets can release chemokines such as CXCL4, CXCL5, and CCL5 on vascular cell surfaces, triggering atherogenesis." (PMID 34357044, 2021).
co-infection (19 papers, 2011 to 2025). "On the other hand, lower levels of MIG and CXCL8 were observed among NC compared to the HIV group, and higher levels of CCL5 in NC compared to the co-infection group." (PMID 37999614, 2023). "Third, we were unable to draw conclusions with regard to the association between CCL5 haplotype D and HIV/HCV co-infection because of low proportion of HIV monoinfected subjects." (PMID 27304910, 2016). "We have previously evaluated the associations between the receptor of CCL5 (CCR5) and another ligand for CCR5 (CCL3L1) genetic variability and the susceptibility to HIV and HCV among PWID in terms of co-infection." (PMID 27304910, 2016). "The chemokine CCL5 was upregulated by S. suis, but considerably more activated by virus and co-infection, as suggested by microarray results." (PMID 24708855, 2014). "It has been reported that in co-infection, the action of anti-inflammatory cytokines may influence the reduced expression of CCL5 and other molecules." (PMID 37999614, 2023). "suis co-infection potentiates the up-regulation of IL-6, CCL5 and TNF-α." (PMID 27213692, 2016). "Co-infection of monocytes with PRRSV-2 strain IAF-Klop and S. suis led to synergistic effects on the expressions of IL-6, CCL5, and TNF-α, and additive effects on productions of CCL4, CCL14, CCL20, IL-15, and PTGS2 (COX-2)." (PMID 38547254, 2024). "An analysis of the serum levels of CCL2, CCL5, MIG, and IP-10 between co-infection and HIV patients highlighted higher levels of these chemokines in the HIV group." (PMID 37999614, 2023). "The chemokines CCL2, CCL5, MIG, and IP-10 exhibited higher levels in the HIV group compared to co-infection." (PMID 37999614, 2023). "CCL5 was also significantly increased in Em-infected mice, although co-infection with Bb had no additional impact on levels of CCL5 in the bone marrow." (PMID 39229265, 2024). "Furthermore, higher levels of CCL2, CCL5, MIG, and IP-10 in the HIV group, and greater connectivity among the chemokines in the co-infection group, suggest that the Leishmania spp." (PMID 37999614, 2023). "However, in the co-infection mouse model employing the reduced viral dose, the neutralization of IFN-γ and IFN-γ together with IL-6 had clear effects on the concentrations of TNF-α, CCL-5, IL-1ß, and GM-CSF." (PMID 31474978, 2019). "Interestingly, a clear synergistic effect on IL-6, CCL5 and TNF-α up-regulation could be observed after co-infection." (PMID 27213692, 2016).
ischemic stroke (19 papers, 2013 to 2025). A stroke disorder caused by obstruction of blood flow to the brain, due to thrombotic (local blood clot formation) or embolic (due to a blood clot or other material traveling from another site) event. "CCR5 and its ligand, CCL5, are involved in the pathology of ischemic stroke and monocyte recruitment." (PMID 37452512, 2023). "CCL5 inhibition reduces Ly6C+ monocyte infiltration, attenuating classical monocyte‐mediated inflammation in an ischemic stroke model." (PMID 37452512, 2023). "In the good prognosis group of ischemic stroke patients, the CCL5 levels were significantly lower (p = 0.023) at day 1 than at HD." (PMID 36077361, 2022). "In the bad prognosis group of ischemic stroke patients, the CCL5 levels were significantly lower (p = 0.008) at day 1 than at HD." (PMID 36077361, 2022). "CCL5 is an intriguing chemokine that is produced from neural cells after ischemic stroke and has the potential to protect neurons directly or indirectly through the production of neurotrophic factors in peri-infarct areas." (PMID 36077361, 2022). "CCL5 is produced from neurons after ischemic stroke to induce the production of neurotrophic factors in peri-infarct areas." (PMID 27635404, 2016). "One recent study indicated that the level of CCL5 may be predictive of infarct volume outcomes in patients with ischemic stroke." (PMID 41098728, 2025). "The levels of CCL5, however, in the serum of patients with ischemic stroke, arouses controversy." (PMID 37759440, 2023). "Recent research suggests that blockage of the CCL5/CCR5 axis may be a promising target for recovery after ischemic stroke." (PMID 37765263, 2023). "Equally, the increase in CCL5 concentration after ischemic stroke may protect neurons by producing neurotrophic factors in peri-infarct areas." (PMID 37759440, 2023). "By assessing the CCL5 level with the NIHSS scale (NIHSS ≤ 3 or >3) at the hospital admission and discharge, we confirmed that in the group of patients with ischemic stroke with a good prognosis, CCL5 levels were lower, and on the seventh day even with p = 0.032." (PMID 37759440, 2023). "Therefore, we can affirm that CCL5 levels at admission can be used as a prognostic biomarker to predict ischemic stroke patient evolution." (PMID 36077361, 2022). "In addition, if CCL5 levels are neuroprotective the lower levels of CCL5 in hemorrhagic stroke compared with those in ischemic stroke are in agreement with the higher clinical severity of hemorrhagic stroke." (PMID 36077361, 2022). "Regarding whether circulating CCL5 levels climb or fall following ischemic stroke, there are different reports with contradictory data." (PMID 36077361, 2022). "Interestingly, patients with hemorrhagic stroke had lower CCL5 levels than patients with ischemic stroke at every time point (1.41-fold: 30.4%, 1.48-fold: 32.8%, and 1.77-fold: 43.7%, 0-1-HD, respectively; p = 0.014, p = 0.028, and p < 0.001, respectively)." (PMID 36077361, 2022). "In contrast, previous studies found elevated CCL5 content in the blood of ischemic stroke patients may be predictive of 3-month mortality and unfavorable outcomes, pointing to CCL5 as a negative predictor of clinical performance." (PMID 36077361, 2022). "CCL5 levels were much lower in hemorrhagic stroke patients than in ischemic stroke patients." (PMID 36077361, 2022). "Upregulated expression of CCL5 in serum of ischemic stroke patients is controversial." (PMID 24324296, 2013). "There are only a few reports concerning the role of CCL5 in the development of ischemic stroke." (PMID 24324296, 2013). "Interestingly, we found a non-significant trend, which may become significant in larger trials, suggesting a larger decrease in CCL5 levels in ischemic stroke female patients than in their male counterparts." (PMID 36077361, 2022).
ischemic stroke (continued). "Also, many genes encoding chemokines, cytokines and chemokine receptors, which are involved in neuroinflammatory processes in ischemic stroke, were regulated, including Cxcr2 in endothelial cells, Ccl5, Il11 and Il6 in pericytes, Lcn2 in astrocytes and pericytes, and Il1rn in microglia." (PMID 35752654, 2022). "We found that the change in gene expression of CCR3 and ligands (CCL5, CCL11, and CCL24) is positively correlated with infarct volume in our transient rat model of ischemic stroke." (PMID 38332938, 2024). "We measured the change in expression of CCR3 and its ligands (CCL5, CCL11, and CCL24) in the venous blood prior to and after occlusion in our transient rat model of ischemic stroke." (PMID 38332938, 2024). "In summary, ischemic stroke results in upregulated expression of adhesion molecules (P‐selectin, E‐selectin, and ICAM‐1) and chemokines (CCL‐2, CCL‐3, CCL‐4, CCL‐5, and CXCL‐1)." (PMID 37122157, 2023). "Our results have revealed that ischemic stroke results in upregulated expression of adhesion molecules (P‐selectin, E‐selectin, and ICAM‐1) and chemokines (CCL‐2, CCL‐3, CCL‐4, CCL‐5, and CXCL‐1)." (PMID 37122157, 2023). "This study concerned patients with ischemic stroke (AIS), whose CCL5 concentration was measured at various time intervals and was compared with the control group." (PMID 37759440, 2023). "Moreover, Canouï-Poitrine confirmed that, higher systemic levels of CCL5 and CXCL10 in asymptomatic men are independent predictors of ischemic stroke." (PMID 24324296, 2013).
osteosarcoma (18 papers, 2012 to 2024). A usually aggressive malignant bone-forming mesenchymal neoplasm, predominantly affecting adolescents and young adults. "This was consistent with Wang's study, where in an osteosarcoma xenograft tumor model, direct knockdown of CCL5 in tumor cells also significantly inhibited tumor growth and angiogenesis." (PMID 39227943, 2024). "Collectively, these results suggested that c-Myc inhibition can promote the regression of osteosarcoma by increasing the expression and secretion of CCL5, CXCL9, and CXCL10 in tumor tissues." (PMID 35292660, 2022). "Osteosarcoma cells express CCR5 and its engagement by CCL5 leads to the activations of αvβ3 integrin and the migration of osteosarcoma cells by activating NF-kB." (PMID 32630699, 2020). "In osteosarcoma, CCL5/CCR5 interactions act via MEK and ERK, and activate NF-κB, resulting in the activation of αvβ3 integrin." (PMID 32630699, 2020). "Taken together, these results indicate that the CCR5, MEK, and ERK pathway is involved in CCL5-induced migration activity and αvβ3 integrin up-regulation in human osteosarcoma cells." (PMID 22506069, 2012). "We also found that CCL5 increased invasive ability of human osteosarcoma cells through Matrigel basement membrane matrix." (PMID 22506069, 2012). "CCR5 mAb, inhibitor, and siRNA reduced the CCL5-enhanced the migration and integrin up-regulation of osteosarcoma cells." (PMID 22506069, 2012). "In the present study, we used αvβ3 integrin antibody to determine the role of αvβ3 integrin and found that it inhibited CCL5-induced cancer migration, indicating the possible involvement of αvβ3 integrin in CCL5-induced migration in osteosarcoma cells." (PMID 22506069, 2012). "Pretreatment of cells with PI3K (Ly294002), Akt (Akt inhibitor), or PKCδ (Rottlerin) inhibitor partially reduced CCL5-induced cell migration in osteosarcoma cells." (PMID 22506069, 2012). "Here we found that CCL5 increased the migration and expression of αvβ3 integrin in human osteosarcoma cells." (PMID 22506069, 2012). "Taken together, these data suggest that activation of CCR5 receptor, MEK, and ERK are required for CCL5-induced NF-κB activation in human osteosarcoma cells." (PMID 22506069, 2012). "CCL5-induced the migration of osteosarcoma cells were greatly reduced by treatment with MEK inhibitors PD98059 and U0126." (PMID 22506069, 2012). "Furthermore, our work demonstrated that pharmacological inhibition of c-Myc in osteosarcoma can promote T cell trafficking into tumor beds by increasing the expression and secretion of CCL5, CXCL9, and CXCL10." (PMID 35292660, 2022). "High CCL5 levels positively correlate with metastasis and poor prognosis in osteosarcoma." (PMID 32630699, 2020). "Another ligand, CCL5, activates NF-κB and induces cell migration in human osteosarcoma." (PMID 31506064, 2019). "On the other hand, we also found that CCL5 promotes the invasion of osteosarcoma cells." (PMID 22506069, 2012). "CCL5 directed human osteosarcoma cell migration (U2OS and MG63 cells)." (PMID 22506069, 2012). "Therefore, PI3K, Akt, or PKCδ pathways partially involved in CCL5-enhanced cell migration in osteosarcoma." (PMID 22506069, 2012). "Therefore, the other signaling pathways (including PI3K, Akt, and PKCδ) are also partially involved in CCL5-induced cell migration in osteosarcoma cells." (PMID 22506069, 2012). "Therefore, knockdown CCL5 reduces cell migration and αvβ3 integrin expression in human osteosarcoma cells." (PMID 22506069, 2012). "In addition, over-expression of CCL5 shRNA inhibited the migratory ability and integrin expression in osteosarcoma cells." (PMID 22506069, 2012). "We therefore, hypothesized that integrin may be involved in CCL5-directed osteosarcoma cell migration." (PMID 22506069, 2012). "Next, we examined whether ERK involved in CCL5-induced cell migration and integrin expression in human osteosarcoma cells." (PMID 22506069, 2012). "We found that CCL5 increased cell migration in human osteosarcoma cell lines." (PMID 22506069, 2012).